PCNA (proliferating cell nuclear antigen)
Diseases named in the same sentence as PCNA in open-access papers (continued):
Sharing a sentence is not in itself a finding about the gene and the disease.
psoriasis (22 papers, 2015 to 2026). An autoimmune condition characterized by red, well-delineated plaques with silvery scales that are usually on the extensor surfaces and scalp. "IL-17A increased PCNA expression, which was inhibited by TP, thereby suggesting the involvement of TP in suppressing keratinocyte hyperproliferation in psoriasis." (PMID 40365308, 2025). "The increased expression of PCNA and involucrin suggests the presence of hyperkeratosis and parakeratosis, the typical pathological features commonly observed in psoriasis." (PMID 37465147, 2023). "Cell cycle–related antigens Ki67 and PCNA are the most common proliferation markers in the IMQ-induced psoriasis-like mouse model." (PMID 36992832, 2023). "As expected, following TDG treatment, the number of Ki67 and PCNA-positive cells in IMQ-induced psoriasis-like mice decreased significantly, which is consistent with the results of previous studies." (PMID 33995034, 2021). "The expression of HDAC1, SIRT1, p63, and PCNA was compared between patients with psoriasis and healthy controls using immunohistochemistry." (PMID 32825671, 2020). "The expression of HDAC1, p63, and PCNA was significantly higher in the plaque psoriasis group than in the guttate psoriasis group (p < 0.01, p < 0.01, and p < 0.05, respectively)." (PMID 32825671, 2020). "Among the patients with psoriasis, expression of HDAC1, p63, and PCNA was significantly higher in plaque psoriasis than in guttate psoriasis." (PMID 32825671, 2020). "PCNA was expressed lower in the skin lesions of the psoriasis mice treated by MTX, indicating that administration of MTX could effectively improve IMQ-induced keratinocyte differentiation and decrease proliferation of keratinocytes triggered by IMQ." (PMID 33364938, 2020). "Increased expression of HDAC1, together with p63 and PCNA biomarkers, could contribute to the formation of clinical phenotypes of psoriasis." (PMID 32825671, 2020). "Furthermore, there were significant differences in the expression levels of HDAC1 as well as p63 and PCNA between plaque and guttate psoriasis." (PMID 32825671, 2020). "In psoriasis-like lesions in guinea pig ears induced by topical propranolol, injection of angelica polysaccharide (a compound in A. sinensis) increased keratinocyte apoptosis and decreased the expression level of proliferating cell nuclear antigen." (PMID 26413149, 2015). "Topically applied TH1579 alleviated the psoriatic phenotype in the imiquimod-induced psoriasis mouse model by decreasing CD45+, Ly6b+, and CD3+ cell infiltration and downregulating the expression of the proliferation marker PCNA." (PMID 40806307, 2025). "Consistently, RT‒qPCR results showed that K17 KO also downregulated the mRNA levels of the proliferation markers K17, K16, PCNA, Cyclin D1 and key enzymes (GLUT1, PFKM, LDHA, HK2, PKM2, ENO1 and PGK1) in the IMQ-induced psoriasis-like model." (PMID 37497003, 2023). "They found that local application of EGCG can decrease PCNA (proliferating cell nuclear antigen) expression, successfully inhibit IMQ-induced abnormal proliferation of epidermal cells, and alleviate psoriasis signs." (PMID 35163855, 2022). "To observe the pathological characteristics of psoriasis improved by LXJDF, we determined the expressions of PCNA, Ki67, loricrin, and LOX-1 in mice skin using immunofluorescence staining techniques." (PMID 33762935, 2021). "The expression of HDAC1 and keratinocyte proliferative markers, such as p63 and PCNA significantly increased, whereas that of SIRT1 decreased in the basal layer (p < 0.05) of the patients with psoriasis compared to those in healthy controls." (PMID 32825671, 2020). "The results showed that topical application of EGCG can reduce PCNA expression, effectively inhibit IMQ-induced abnormal proliferation of epidermal cells and relieve psoriasis-like appearance." (PMID 27581210, 2016).
psoriasis (continued). "PCNA is used to examine epidermal hyperproliferation in psoriasis and the potential for malignancy in skin lesions, and CCD1 is a key regulator of cell cycle progression in psoriasis, and both are downstream of the Wnt5a/β-catenin pathway genes." (PMID 40365308, 2025). "Using the IMQ psoriasis mouse model in NOS2 KO mice, we found a reduced neutrophilic infiltrate and a lower expression of epidermal Ki67 and PCNA, suggesting that the NOS2 protein expression, which was present at low levels in response to IMQ in control mice, contributes to the psoriatic phenotype." (PMID 38926337, 2024). "The protein expression of the of the proliferation markers PCNA and the anti-apoptotic protein BCL2 was observed to be markedly increased in the IMQ psoriasis induced group, while their expression levels were significantly declined in all the treatment groups used in the current study." (PMID 37010718, 2023). "ESW could distinctly improve IMQ-induced psoriasis in mouse through reducing PASI score, alleviating tissue damage, restoring spleen index, and inhibiting proliferating cell nuclear antigen (PCNA) expression in psoriasis-like skin tissue." (PMID 34603060, 2021). "It was shown that the percentage of PCNA-positive cells in malignant and some non-malignant skin diseases (atopic dermatitis, psoriasis) is from 2- to 5- times higher than in normal skin cells." (PMID 25585689, 2015). "The skin IHC results also confirmed that PCNA and Ki67 levels decreased in both LYS-Low and LYS-High groups, suggesting that LYS treatment could reduce keratinocyte proliferation in mice with psoriasis." (PMID 36992832, 2023). "Moreover, Ki67 expression and the mRNA levels of proliferation markers K17, K16, PCNA, Cyclin D1 and key enzymes (GLUT1, PFKM, LDHA, HK2, PKM2, ENO1 and PGK1) were also decreased in epidermal KCs of the IMQ-induced psoriasis-like model with local application of BI-D1870." (PMID 37497003, 2023).
adenoma (21 papers, 2008 to 2025). A neoplasm arising from the epithelium. "Because the cell proliferating degree between hyperplasia and adenoma is different, expression level of PCNA can be considered as a marker for distinguishing adrenocortical adenoma and adrenocortical hyperplasia." (PMID 18366613, 2008). "In this study, celecoxib appeared to reduce the number of PCNA-positive cells in adenomas and adenocarcinomas." (PMID 40176805, 2025). "Next, we examined PCNA staining in adenomas and adenocarcinomas in celecoxib-treated and untreated groups." (PMID 40176805, 2025). "Both tumor types displayed PCNA-positive cells overall, with adenocarcinomas showing a higher prevalence than adenomas." (PMID 40176805, 2025). "Histological analysis of enlarged ΔS6 livers revealed the presence of biliary malformations such as bile duct hamartomas as well as adenomas that almost invariably contained PCNA- and phospho-Rps6Ser235/6-positive cells." (PMID 36656901, 2023). "PCNA is a cell proliferation marker that is stained in adenomas and adenocarcinomas of the lungs, TML, and TML lung metastases." (PMID 36608059, 2023). "In concordance with this finding, the expression of other genes involved in the control of cell proliferation such as Ki-67 (p = 0.5438) and PCNA (Proliferating cell nuclear antigen p = 0.6637), was found to be the same among the different adenoma subtypes." (PMID 35260162, 2022). "In contrast, the frequency of proliferating cell nuclear antigen (PCNA)-positive cells increased in adenoma, HCC, and CCC, which was reduced probiotics treatment." (PMID 36171333, 2022). "Compared with the control group, adenoma organoids showed increased cell viability and more Ki67- and PCNA-positive cells." (PMID 34585630, 2021). "The results showed that administration of CORT significantly elevated Ki-67 and PCNA expression in colonic epitheliums of neoplasms, including pathological type adenoma with low grade dysplasia, adenoma with high grade dysplasia and ACA." (PMID 30665389, 2019). "The results showed that these PCNA positive proliferative stromal cells were mostly identified as vimentin positive fibroblasts in the adenoma/CRC stroma." (PMID 28484082, 2017). "In order to examine the relationship between cell proliferation and ERK1/2 activation in mouse lung tumors, double‐immunohistochemical staining for pERK1/2 and PCNA was performed in a total of 61 lesions (13 hyperplasias, 34 adenomas, and 14 adenocarcinomas)." (PMID 26864819, 2016). "A strong expression of PR, EGFR and PCNA was observed in the carcinoma component of carcinomas in adenomas, in contrast to the peripheral adenoma component." (PMID 25364399, 2014). "Although, the adenomas tended to be larger than the other types of tumors, all of the immunohistochemical labeling indices (PCNA, ER, PR and EGFR) tended to be lower when compared with the carcinomas in the adenomas and adenocarcinoma groups." (PMID 25364399, 2014). "The only statistically significant correlation between tumor size and PCNA expression was observed in the adenomas." (PMID 25364399, 2014). "In this study, Riccardin D prevented adenoma growth and induced apoptosis of intestinal polyps by decreasing of PCNA and cyclin D1 in APCMin/+ mice." (PMID 22432006, 2012). "The results of this study show that combined detection of the expression of FHIT, Ki-67 and PCNA in hypercortisolism of adrenocortical carcinoma, adenoma and hyperplasia is valuable." (PMID 18366613, 2008). "From hyperplasia, adenoma to carcinoma, while the degree of cell proliferating is increasing, the positive rate of PCNA expression is also increasing too." (PMID 18366613, 2008). "Expression of Ki-67 and PCNA in adrenocortical carcinoma is the highest, in hyperplasia is the lowest, and in adenoma is the middle." (PMID 18366613, 2008). "The expression level of PCNA in adrenocortical hyperplasia is lower than those in adenoma and carcinoma." (PMID 18366613, 2008).
adenoma (continued). "This reduction in PCNA expression suggests that celecoxib may suppress tumor cell proliferation, which could contribute to its inhibitory effect on adenoma-to-adenocarcinoma progression." (PMID 40176805, 2025). "Celecoxib appeared to reduce the number of PCNA-positive cells in adenomas and adenocarcinomas." (PMID 40176805, 2025). "The adenomas of ApcMin/+mice showed higher staining of PCNA (proliferating cell nuclear antigen) than ApcMin/+mice with specific deletion of COX-1 in the platelet; PCNA is an auxiliary protein for DNA polymerase that reaches maximal expression during the S phase of the cell cycle." (PMID 39764464, 2024). "Moreover, loss of epithelial GPR65 resulted in decreased expression of proliferative markers, including Ki67 and PCNA, in adenoma-bearing colon tissues." (PMID 37749885, 2023). "Virtually all adenoma cells were positive for the cell proliferation marker PCNA." (PMID 26959117, 2016). "In an earlier NNK‐induced mouse lung carcinogenesis study, the expression levels of pERK and PCNA, assessed as a marker of cell proliferation, were higher in adenocarcinomas than in adenomas by immunohistochemical staining, suggesting a positive correlation between ERK activity and cell division." (PMID 26864819, 2016). "Similarly, the carcinoma components of carcinomas in adenomas demonstrated significant correlations between tumor size and PCNA expression, as well as between EGFR and PR expression." (PMID 25364399, 2014). "The results of double IHC demonstrated that many of the PCNA positive cells in the control, adenoma and CRC stromal cells were vimentin positive fibroblasts and confirmed that vimentin positive fibroblasts in the adenoma/CRC stroma might have a high proliferative capacity." (PMID 28484082, 2017). "Although TTF-1, Ki67, and PCNA are upregulated in the thyroid specimens of DMD-treated rats, especially in the regions with hyperplasia and adenoma formation, they are in relatively lower levels in the two resveratrol-treated groups." (PMID 29495605, 2018). "Nuclear staining of PCNA, a marker of cell proliferation, was equally increased in WT and MDR1A KO adenomas, when compared to control tissues." (PMID 28686677, 2017). "Lung tumors, including adenomas, carcinomas in adenomas and adenocarcinomas, were obtained and analyzed by immunohistochemistry for the expression levels of the receptors, ER, PR and EGFR, and PCNA." (PMID 25364399, 2014). "We also counted Ki-67-stained cells and PCNA-stained cells and found a larger number of positive cells in AOM/DSS + Vehicle adenomas than in AOM/DSS + Lb. plantarum AY01 adenomas, suggesting that Lb. plantarum AY01 culture supernatant inhibits the proliferation of tumor cells." (PMID 39132155, 2024). "In normal, hyperplasia and adenoma, the expression of both pERK1/2 and PCNA was negative or observed locally." (PMID 26864819, 2016). "The expression levels of FHIT, Ki-67 and PCNA in hypercortisolism of various adrenocortical diseases are useful for distinguishing adrenocortical carcinoma, adenoma and hyperplasia but none of them are high characteristic." (PMID 18366613, 2008). "Similarly, in adenocarcinomas with strong pERK1/2, the level of PCNA expression was increased as compared to that in hyperplasias and adenomas without activated ERK1/2." (PMID 26864819, 2016). "The levels of Ki67 and PCNA in the DMD alone group were higher than that of the resveratrol-treated groups and their levels in the hyperplasia and adenoma tissues were stronger than the surrounding noncancerous tissues." (PMID 29495605, 2018).
cyst (21 papers, 2012 to 2024). A sac-like closed membranous structure that may be empty or contain fluid or amorphous material. "Conversely, in Cy/+ kidneys, robust samcystin staining was observed in cyst-lining epithelial cells, accompanied by loss of apical localization and increased numbers of proliferating cell nuclear antigen-positive cells in cyst-lining epithelia." (PMID 38397964, 2024). "As enhanced proliferation of cyst epithelial cells contributes to cyst formation, we stained kidney specimens with the antibody of PCNA, a proliferative marker." (PMID 39333852, 2024). "Quantification of the percentage of PCNA+ cyst-lining cells suggested a significant reduction in kidneys treated with CCB02 and PJ34 compared with control." (PMID 38385746, 2024). "Our snRNA-seq results showed that PCNA, Cyclin D1 and Caspase3 levels were increased in cyst cells compared to all other kidney cells." (PMID 37583898, 2023). "Accordingly, the severely germ cell-depleted cyst reveals the conclusion of apoptotic death and PCNA’s very different role there in the penultimate stage of apoptotic body formation." (PMID 35672487, 2022). "To evaluate Notch3’s effect on proliferation and cyst formation, we measured proliferation using PCNA and MCM-2." (PMID 35055068, 2022). "The cells lining the cysts in Pkd1 mice showed a relative increase in the number of PCNA‐positive cells in cyst epithelium as compared to wild‐type mice (fourth panel)." (PMID 30675765, 2019). "To better establish the role of intercalated cells in cyst epithelia proliferation in these Tsc knockout mice, we performed double labeling with H+‐ATPase and proliferating cell nuclear antigen (PCNA) in kidneys of Aqp2CreTsc2 and Ren1cCreTsc1 mice." (PMID 30675765, 2019). "Further, this co-expression of N3 and PCNA was shown also in cyst-lining epithelia of PKD1RC/del2 kidneys." (PMID 29463793, 2018). "PCNA-positive cells were increased in cyst-lining epithelia of cpk kidneys with many cells expressing both N3 and PCNA." (PMID 29463793, 2018). "In the present study, the high expression of PCNA in the suprabasal layer of KCOT in comparison to other cysts indicates that the suprabasal layer of this cyst is a proliferative component and explains the different growth patterns." (PMID 24551811, 2013). "The number of PCNA-positive kidney tubule/cyst cells per 20 X power field was 121 ± 15 in vehicle-treated PCK kidneys and 67 ± 9 in doxycycline-treated PCK rat." (PMID 22963260, 2012). "CXB remarkably decreased the increases in kidney weight, serum 6-keto-PGF-1α, serum TXB2, BUN, SCr, the cyst index, the fibrosis index, leukocyte infiltration and PCNA expression." (PMID 22415852, 2012). "The percentage of PCNA-positive cyst epithelial cells was also downregulated by decitabine." (PMID 39333852, 2024). "Since over-proliferation of epithelial cells is a driver of cyst progression, we performed immunofluorescence staining of P7 kidney sections using anti-proliferating cell nuclear antigen (PCNA), a nuclear marker for cell turnover." (PMID 36920028, 2023). "PCNA, Cyclin D1 and Caspase3 were upregulated in cyst cells compared to all other kidney cells." (PMID 37583898, 2023). "The scattered anomalously PCNA-labeled dying spermatogonia and classic apoptotic morphologies that border the cyst lumen reflect the deaths of single spermatogonia, which is perhaps the closest link between them in this in situ study of highly dynamic processes." (PMID 35672487, 2022). "In addition, treatment with GW4869 decreased cyst-lining epithelial and surrounding cell proliferation as examined by PCNA staining and the expression of PCNA as examined by qRT-PCR." (PMID 34315885, 2021).
cyst (continued). "Similarly, the cyst epithelium in Ren1cCreTsc1 mice showed many H+‐ATPase expressing cells that also displayed positive staining for PCNA (third panel), a pattern very similar to Aqp2CreTsc2 mice." (PMID 30675765, 2019). "Immunocytochemical markers for lectins (Ulex europaeus agglutinin I and Bandeiraea simplicifolia agglutinin I) and proliferating cells (proliferating cell nuclear antigen and Ki-67) may be helpful in differentiating UA from any other cyst." (PMID 25202458, 2014). "Similarly, cyst-lining epithelial cells expressed both N3 and PCNA." (PMID 29463793, 2018). "Cyst growth has been shown to be mediated by the proliferation of the cyst-lining cells, which was confirmed on the CAM through a significant number of PCNA-positive cells." (PMID 35892566, 2022). "In contrast, ISO-1 significantly reduced both, expression of MIF and PCNA, suggesting that MIF-dependent cyst enlargement is due to increased cyst cell proliferation." (PMID 32885302, 2020). "CXB markedly reduced the cyst index, the fibrosis index, leukocyte infiltration, BUN, SCr, serum 6-keto-PGF-1α, TXB2 and renal PCNA expression in Han:SPRD rat." (PMID 22415852, 2012). "Additionally, effects of CXB on kidney weight, the cyst index, the fibrosis index, blood urea nitrogen (BUN), serum creatinine (SCr), serum 6-keto-PGF-1α, serum thromboxane-2 (TXB2) and renal PCNA expression were assessed in Han:SPRD rat, a well-characterized rodent model of PKD." (PMID 22415852, 2012).